UPK2 (uroplakin 2)
Description:
Component of the asymmetric unit membrane (AUM); a highly specialized biomembrane elaborated by terminally differentiated urothelial cells. May play an important role in regulating the assembly of the AUM (By similarity).
Synonyms: UP2; UPII; MGC138598
Tractability: Antibody: UniProt places it where antibodies can reach, with high confidence; its Gene Ontology location is reachable by antibodies, with high confidence; UniProt predicts a signal peptide or a membrane-spanning region. PROTAC: ubiquitination databases record sites on it.
Gene: Protein-coding gene on chromosome 11 (118,925,164 to 118,958,559, forward strand). Ensembl gene ENSG00000110375.
Subcellular location: Cell membrane
Gene Ontology:
Molecular function: protein binding
Biological process: epithelial cell differentiation
Cellular component: extracellular exosome; apical plasma membrane; plasma membrane
Genetic constraint (gnomAD): Loss-of-function variants: 19 observed, 15.56 expected, observed/expected ratio (o/e) 1.22, 90% interval 0.85 to 1.75. The upper end of that interval is the gene's LOEUF score, 1.75, which puts it in group 6 of 6, group 1 being the genes least tolerant of losing a copy. Missense variants: 232 observed, 245.73 expected, observed/expected ratio (o/e) 0.94, 90% interval 0.85 to 1.05. Synonymous variants: 102 observed, 104.9 expected, observed/expected ratio (o/e) 0.97, 90% interval 0.83 to 1.15.
Homologues: Orthologues: chimpanzee UPK2 (99% identical), macaque UPK2 (94% identical), dog UPK2 (91% identical), pig UPK2 (90% identical), mouse Upk2 (87% identical), rabbit UPK2 (87% identical), rat Upk2 (87% identical), guinea pig UPK2 (84% identical).
Diseases named in the same sentence as UPK2 in open-access papers:
UPK2 is named in the same sentence as 29 diseases in open-access papers, as found by Europe PMC text mining. Sharing a sentence is not in itself a finding about the gene and the disease. The quoted sentences say what the papers report.
bladder cancer (21 papers, 2007 to 2025). "Prior studies examining the effect of mutant FGFR3 in bladder cancer have routinely constitutively expressed the gene transgenically under control of the Upk2 promoter." (PMID 38226620, 2024). "The bladder stromal cells did not express UPK2, a marker of bladder urothelial cells; however, UPK2 was expressed in normal bladder epithelial cells and bladder carcinoma cells, with the lowest expression in T24 cells." (PMID 34662721, 2022). "UPK2 has been used as CTC markers of bladder cancer and got a satisfying result, which indicated a promising role for UPK2 mRNA detection using the circulatory blood of patients with urothelial cancer as a new staging marker." (PMID 34422643, 2021). "Expression of two copies of mutant HRAS results in the development of noninvasive bladder cancer at 6 months, and we saw identical urothelial regression in these animals following Upk2-Cre mediated Foxa1 KO." (PMID 30670749, 2019). "Indeed, creation of the Upk2-HRAS* model of bladder cancer confirmed a role for mutant HRAS in noninvasive bladder cancer." (PMID 30670749, 2019). "The luminal marker GATA3, urothelial marker CK20, urothelial carcinoma marker UPK2, and squamous epithelium marker p40 were identified, indicating that the PDO of human bladder cancer was successfully constructed." (PMID 39651805, 2025). "Further analysis of the 3 independent bladder cancer datasets have identified ACOX1, UPK2, TRAK1, PLEKHG6 and MT1X genes had their expression significantly correlated with that of DAPK1." (PMID 28388658, 2017). "Knockdown of DAPK1 in bladder cancer T24 cells resulted in downregulation of ACOX1, UPK2 and TRAK1." (PMID 28388658, 2017).
urothelial carcinoma (15 papers, 2016 to 2025). A malignant neoplasm derived from the transitional epithelium of the urinary tract (urinary bladder, ureter, urethra, or renal pelvis). "Consistent with the basal differentiation in Kmt2c/d KO urothelium, the urothelial carcinoma models exhibited basal phenotype, corroborated by KRT5 positivity and loss of UPK2 by IHC." (PMID 39806204, 2025). "UPK2 is a component of urothelial plaques, specialized membrane domains in urothelial superficial (umbrella) cells, and is used as a relatively specific marker for urothelial carcinomas." (PMID 39917902, 2025). "UPK2 exhibits excellent specificity for urothelial carcinoma (UC)." (PMID 35027056, 2022). "In a recent study of nodular hypoplasia formation in Upk2-HRAS transgenic mice, overexpression of PKM2 was identified as the principal tyrosine-phosphorylated protein in the genesis of urothelial carcinomas." (PMID 31120964, 2019).
urothelial hyperplasia (3 papers, 2016 to 2022). Hyperplasia of the transitional epithelium of the urinary tract. "We utilized the requirement of Forkhead box A1 (Foxa1) for transcriptional activation of the Upk2-promoter to temporally control the expression of Upk2-HRAS* oncogene, an inducer of urothelial hyperplasia in transgenic mice." (PMID 30670749, 2019). "Our results indicate that maintenance of urothelial hyperplasia in Upk2-HRAS* mice depends on continuous expression of Foxa1 and activated HRAS, and that mutated receptor tyrosine kinases, FOXA1 and/or other downstream effectors may mediate oncogene addiction in urothelial hyperplasia." (PMID 30670749, 2019). "Weaknesses of this study include our inability to measure the impact of Foxa1 KO on urothelial proliferation in real time, and the fact that we did not use an inducible system to reversibly control Upk2-HRAS* expression after the development of urothelial hyperplasia." (PMID 30670749, 2019).
Autoimmunity (1 paper, 2013). The occurrence of an immune reaction against the organism's own cells or tissues. "Those sequences (human UPK1A 171–179, sequence FTSAFRAAT, and human UPK2 117–125, sequence ISYLVKKGT) suggest that uroplakins 1A and 2 are possible targets for T cell-mediated autoimmunity leading to IC/PBS in humans." (PMID 23977210, 2013). "Our model of uroplakin 2-immunized mice provided bladder specific autoimmunity, but those mice did not demonstrate enhanced pelvic pain responses to noxious stimuli, thus missing one of the major symptoms of IC/PBS." (PMID 23977210, 2013).
colorectal adenocarcinoma (1 paper, 2025). The most common type of colorectal carcinoma. "Interestingly, UPK2 (uroplakin 2) was also frequently expressed in micropapillary colorectal adenocarcinoma." (PMID 39917902, 2025).
prostate carcinoma (1 paper, 2025). A carcinoma that arises from epithelial cells of the prostate gland. "Proteins unique to the U-EVs of the GS 6–7 group included several keratins, corneodesmosin, the cell–cell adhesion protein desmoplakin, and uroplakin-2, which is a marker for urothelial and prostate carcinoma." (PMID 40725142, 2025).
tumor (26 papers, 2008 to 2025). "Results showed that some of the proteins found in EVs were shared among these cancer types, while others were tumour‐specific, and with respect to UC, the EVs expressed high levels of UPK1A, UPK1B, UPK2 and UPK3B." (PMID 35838333, 2022). "Our analysis identified seven tumour suppressor genes (ITGA7, SLC45A1, TPPP, SCN4A, GIPR, SOGA3 and RAB6B) and six oncogenes (SAT1, SERPINE1, UPK2, SYT12, RASAL1 and CDH3) with significant false discovery rate (FDR)-adjusted P values (q-value) of less than 0.05." (PMID 38429478, 2024). "Among them, RAB11A expression was correlated with the expression of UPK1A and UPK2, two urothelium marker genes also down-regulated in this tumor group (data not shown)." (PMID 22724020, 2012). "On the contrary, pSTAT3+ tumor cells were regularly negative for the luminal markers UPK2 and CK20." (PMID 31438567, 2019). "Whole-slide analysis should be performed on samples that are negative for UPK2, because compared to TMA analysis, this method can prevent effects of tumor heterogeneity." (PMID 35027056, 2022).
urological diseases (2 papers, 2007 to 2021). "This type of analysis also revealed PAR-1 dependent genes (upk2, jundD, ptprc, and nfkbp1a) encoding proteins associated with renal and urological diseases." (PMID 17397547, 2007).
adenocarcinoma (1 paper, 2025). A common cancer characterized by the presence of malignant glandular cells.
UPK2 also shares sentences with these, for which no sentence is quoted: cancer (9 papers); bladder tumor (3); hydronephrosis (2); hyperplasia (2); apocrine carcinoma (1); benign prostatic hyperplasia (1); bladder (1); bladder urothelial carcinoma (1); breast carcinoma (1); colon cancers (1); colorectal cancer (1); interstitial cystitis (1); Lobular Carcinoma (1); lung carcinoma (1); metastatic carcinoma (1); papillary carcinoma (1); prostate adenocarcinoma (1); urinary tract infection (1); urolithiasis (1); urothelial cell carcinoma (1).